BAALC-AS1 (BAALC antisense RNA 1)
Synonyms: lncFZD6; FZD6-DT; LOC105369147
Gene: Long non-coding RNA gene on chromosome 8 (103,153,394 to 103,371,410, reverse strand). Ensembl gene ENSG00000247081.
Diseases named in the same sentence as BAALC-AS1 in open-access papers:
BAALC-AS1 is named in the same sentence as 2 diseases in open-access papers, as found by Europe PMC text mining. Sharing a sentence is not in itself a finding about the gene and the disease.
BAALC-AS1 shares sentences with these, for which no sentence is quoted: liver cancer (1 paper); tumor (1).